ARG1 (arginase 1)
Diseases named in the same sentence as ARG1 in open-access papers (continued):
Sharing a sentence is not in itself a finding about the gene and the disease.
Hypertension (19 papers, 2013 to 2025). The presence of chronic increased pressure in the systemic arterial system. "A switch to macrophages with an M2 phenotype with increased CD206 and Arg-1 expression at 7–14 days after angiotensin II infusion has been described in a mouse model of hypertension, which was associated with elevated blood pressure and fibrosis." (PMID 33154752, 2020). "When we evaluated the associations between the CRP-related SNPs with cardiovascular disease phenotypes, rs9375813 (ARG1) showed a marginal association with hypertension (P = 0.0440)." (PMID 24763700, 2014). "However, in another case-control study, the variant genotype of rs2781666 at ARG1 locus was significantly linked to the increased arginase activity in patients diagnosed with essential hypertension (EH)." (PMID 30233283, 2018). "The SNP in ARG1 (rs9375813) showed a marginal association with hypertension (P = 0.0440)." (PMID 24763700, 2014). "Comparative analysis revealed a significant upregulation of iNOS coupled with the down-regulation of Arg1 in these brain areas among hypertension (HTN) and Pb-exposed groups relative to those in control animals." (PMID 41404489, 2025). "Our findings indicate that enhancement of vascular ARG activity induced by ARG1 isoform has a key role in salt-induced hypertension." (PMID 23908657, 2013). "Hypertension was induced in wild type (WT), partial ARG1+/− knockout (KO), and complete ARG2−/− KO mice by uninephrectomy and deoxycorticosterone acetate (DOCA)-salt treatment for 6-weeks." (PMID 23908657, 2013). "Increased arginase-1 activity, which can be triggered by ROS, TNF-α, and angiotensin II through AT1R, has been associated with vascular dysfunction in conditions such as hypertension, and acute myocardial infarction." (PMID 40647187, 2025). "Elevated inducible nitric oxide synthase and reduced arginase-1 protein expressions were observed in the prefrontal cortex, hippocampus, and hypothalamus of the Pb, hypertension (HTN), and Pb+HTN groups, with the most pronounced alterations occurring in the prefrontal cortex." (PMID 41404489, 2025). "Furthermore, our group also demonstrated ARG1 dysregulation in various tissues and organs of diabetic and hypertension disease models." (PMID 31205583, 2019). "To explore the possibility of whether these ARG1 polymorphisms may be associated with a lower risk of CVD, we evaluated the association of ARG1 SNPs with a history of MI, CHD, and hypertension in the discovery subjects." (PMID 24763700, 2014). "However, ARG1 has been shown to modulate vascular tone in disease conditions such as diabetes, ischemia reperfusion, and hypertension." (PMID 23908657, 2013). "However, whether ARG1 and ARG2 differ in the development of hypertension warrants further investigation." (PMID 36209203, 2022). "Indeed, arginase 1 and 2 mRNA expression exhibited an increasing tendency in hypertension, which was not affected by class I HDAC inhibitors." (PMID 30830950, 2019).
Granuloma (18 papers, 2010 to 2025). A compact, organized collection of mature mononuclear phagocytes, which may be but is not necessarily accompanied by accessory features such as necrosis. "A reduced MBT load was observed in ARG1-deficient mice, also showing that liver granulomas in BCG-infected mice produced more bactericidal nitrotyrosine after host arginase inhibition." (PMID 37185755, 2023). "In contrast, macrophages stimulated by Th2 cytokines, especially IL-13, become alternatively activated and produce arginase-1 (arg-1) and proline, higher levels of which are associated with larger granulomas and increased fibrosis." (PMID 20663176, 2010). "Interestingly, loss of ARG1 in Nos2−/− mouse hematopoietic cells resulted in increased necrotic granulomas and increased mycobacterial load." (PMID 37185755, 2023). "Together, we here introduce an experimental TB model that displays many features of centrally necrotizing granulomas in human post-primary TB and demonstrate that IL-13/IL-4Rα-dependent mechanisms leading to arginase-1 expression are involved in TB-associated tissue pathology." (PMID 24979482, 2014). "Previously, we have demonstrated that foamy macrophages in necrotizing granulomas express typical macrophage polarization markers, either Nos2 or Arg1, suggesting their differentiation into a pro-inflammatory or anti-inflammatory state." (PMID 40843005, 2025). "In NHP granulomas, the Arg1+ macrophages were found primarily in the outer layer suggesting their role in limiting lung pathology." (PMID 35682679, 2022). "Perhaps, gradual accumulation of the Arg1+ macrophages during the chronic course of the M.av granuloma progression represents an adaptive macrophage reaction to limit lung tissue damage by NO." (PMID 35682679, 2022). "In tuberculosis granulomas, arginase 1-expressing M2 macrophages localize to the outer regions of granulomas, while NOS2-expressing M1 macrophages can be found in the inner regions." (PMID 28223985, 2017). "In contrast, Arg-1 expression was undetectable in the lungs of Mtb-infected wild-type mice but was very prominent in lung granulomas of IL-13tg mice." (PMID 24979482, 2014). "In the liver, however, Arg1-positive macrophages suppress excessive Th2 responses (and perhaps other types of T cell responses), decreasing granuloma size, fibrosis, and hepatomegaly, and even preventing death." (PMID 23637937, 2013). "Although we detected high expression of IDO-1 in macrophages in the center of granulomas from TB as well as TB/HIV co-infected tissues, arginase-1 expression was mostly confined to the T cell rich areas localized at the periphery of the TB granulomas, surrounding the cores of the lesions." (PMID 36591229, 2022). "Interestingly, iNOS- and Arg-1–producing cells were mostly localized at the periphery of the TB granulomas in cells with a mononuclear morphology, whereas IDO-1 expression was detected primarily inside the granulomas." (PMID 35092727, 2022). "However, the role of ARG1 in mediating immune cell functions appears to depend on the specific granuloma microenvironment." (PMID 30914513, 2019). "Conversely, abrogation of Arg1 expression in hypoxic macrophages where iNOS was rendered ineffective resulted in exacerbated lung granuloma pathology and bacterial burden, suggesting that Arg1 could also play a positive role in the control of M. tuberculosis." (PMID 25505468, 2014). "Here, necrotic centres of the granulomas were typically surrounded by Arg-1-expressing cells." (PMID 24979482, 2014). "Moreover, inhibition of both ARG1 and iNOS exacerbates lung granuloma pathology and the bacterial burden in Mtb infected mice, possibly due to uncontrolled Th1 cell responses, while S. mansoni-induced ARG1 exacerbates lung inflammation upon co-infection with Mtb." (PMID 39863828, 2025).
Granuloma (continued). "This was accompanied by the development of centrally necrotizing granulomas in the lungs of L-NIL-treated mice, surrounded by Arg-1-expressing cells, very similar to the pathology observed in Mtb-infected IL-13tg mice." (PMID 24979482, 2014). "In a mouse model, the expression of arginase-1 was shown to be modestly protective in granulomas in the absence of iNOS, and simultaneous Arg1 and iNOS inactivation resulted in exuberant necrotic inflammation." (PMID 26542392, 2016). "In addition, in situ imaging of non-human primate granulomas confirmed abundant presence of arginase-1 expressing epithelioid-like cells in the more distal cell layers from the necrotic core of the granulomas." (PMID 36591229, 2022). "In non-necrotic granulomas, ARG1+ cells were distinct from PLIN2+ cells." (PMID 36237431, 2022). "Moreover, the proportion of ARG1+ cells in non-necrotic granulomas was smaller than that in Rim of necrotic granulomas." (PMID 36237431, 2022). "TB granulomas upregulate iNOS, endothelial NOS (eNOS), and arginase 1 (Arg1) compared to non-granulomatous tissue." (PMID 37367586, 2023).
liver cancer (18 papers, 2020 to 2026). An epithelial or non-epithelial malignant neoplasm that arises from the liver. "Another potential prognostic marker in metabolic syndrome/NASH-associated human liver cancer is arginase 1 (ARG1), whose expression is downregulated in NAFLD/NASH-HCC." (PMID 37760534, 2023). "To further investigate the role of unmetabolized arginine in HCC, we first screened a panel of human liver cancer cell lines for loss of ARG1, AGMAT, and arginine synthesis enzymes to find an in vitro experimental system that phenocopies L-dKO tumors, selecting the SNU-449 cell line." (PMID 37804830, 2023). "Furthermore, from the public clinical microarray database of TCGA, we found that the expression of BMP2 in liver cancer tissues was associated with Arg1 and IL6, the activation marker of MDSCs." (PMID 32195173, 2020). "Alpha-fetoprotein (AFP), Osteopontin (OPN), Glypican-3 (GPC-3) and Arginase-1 (Arg-1) are common primary liver cancer related biomarkers." (PMID 37575092, 2023). "Strong GPC3 fluorescence signal intensity (green) was visible on the surface of human liver cancer Hep-G2 cell membrane and in the intercellular space, but the intensity of ARG1 (yellow) signal was comparatively low." (PMID 35331259, 2022). "Glypican-3 and arginase-1 are among the most effective diagnostic markers for HCC, the positive staining thus confirming the liver cancer identity of the transformed iHeps." (PMID 34302118, 2021). "Arg-1 is mainly produced in the liver tissue, the main objective of this study was to evaluate the expression pattern of Arg-1 and HepPar-1 in patients with liver cancer." (PMID 32854754, 2020). "Results from this systematic review will inform clinical practice and research on ARG-1 and liver cancer." (PMID 32118719, 2020). "To further investigate the hypothesis that unmetabolized arginine promotes growth of liver cancer cells, we cultured ARG1/AGMAT-expressing SNU-449 cells in the presence or absence of high levels of arginine or several arginine-related metabolites." (PMID 37804830, 2023). "In order to further verify the causal relationship between air pollution and primary liver cancer, we selected four biomarkers (Alpha-fetoprotein, Osteopontin, Glypican-3 and Arginase-1) which are closely related to primary liver cancer as the outcome and conducted MR Analysis again." (PMID 37575092, 2023). "However, ARG1/AGMAT-controlled arginine levels impacted liver cancer cell metabolism beyond central energy metabolism." (PMID 37804830, 2023). "From our results, downregulation of ARG1 may become an important marker associated with decrease of survival in metabolic syndrome and NASH-associated human liver cancer patients." (PMID 33092030, 2020). "Moreover, the importance of ARG1 and AGMAT expression in HCC patients is underscored by the finding that loss of ARG1 and/or AGMAT is associated with reduced survival based on a TCGA liver cancer dataset." (PMID 37804830, 2023). "A recent study showed that β-catenin can down-regulate ARG1 expression by suppressing liver-enriched transcription factors C/EBPA and FOXA1 in liver cancer cell lines." (PMID 41512056, 2026). "Thus, while ARG1/AGMAT expression modulates arginine abundance and tumour growth in liver cancer, there appears to be additional metabolic complexity regarding the sources and sinks of arginine to be parsed in future work." (PMID 39871876, 2024). "Immunoblotting confirmed loss of ARG1 and AGMAT and increased levels of RBM39 and ASNS in tumors of liver cancer patients compared to adjacent non-tumor tissue." (PMID 37804830, 2023). "In these samples, both GPC3 and ARG1 were expressed in the liver cancer tissue but not in normal liver tissue, and the expression of GPC3 or ARG1 in HCC tissue were higher than that in normal tissue." (PMID 35331259, 2022).
liver cancer (continued). "Therefore, we generated an animal model of liver cancer by injecting mouse with CCl4 and then excised tissue samples from the mouse at the three typical stages of HCC progression (liver fibrosis, liver cirrhosis, and HCC) for immunofluorescence staining of GPC3 and ARG1." (PMID 35331259, 2022). "The IHC experiments indicated that the liver cancer tissues induced by pT3-TRIM71 alone did not express Ck7 and Ck19, and β-catenin was primarily localized in the cytoplasmic matrix, with tumors expressing AfP and Arg1." (PMID 39267787, 2024). "In our results, we found that BMP2 signaling could enhance the expression of the Arg1 and IL6 in bone marrows, rather than iNOS, IL8, and IL10, indicating that BMP2 inducing MDSCs expansion might enhance liver cancer growth via IL6." (PMID 32195173, 2020).
arginase deficiency (16 papers, 2012 to 2025). "Arginase deficiency (ARG1d) is an inborn error of metabolism caused by pathogenic variants in ARG1 gene, which causes a defective hydrolysis of arginine (Arg) to urea and ornithine." (PMID 40678074, 2025). "Arginase 1 (ARG1) deficiency manifests with hyperargininemia and progressive neurological impairment." (PMID 39669610, 2024). "Therrell et al9 estimated the birth prevalence of ARG1 deficiency as 1 in 119,500 based on data from all US states that screened newborns for hyperargininemia between 1999 and 2015." (PMID 39669610, 2024). "Arginase deficiency is a rare autosomal recessive urea cycle disorder (UCD) caused by mutations in the ARG1 gene encoding arginase that catalyses the hydrolysis of arginine to ornithine and urea." (PMID 35281666, 2022). "Argininemia or arginase 1 (ARG1) deficiency (MIM number: 207800) is an autosomal recessive disorder caused by a defect in ARG1 (L-arginine-urea-hydrolase; EC 3.5.3.1) in the liver." (PMID 34646736, 2021). "Hyperargininemia in ARG1 deficiency is related to elevated L-arginine levels and alterations in L-arginine metabolites." (PMID 34646736, 2021). "We described a male child with hyperargininemia and progressive spastic diplegia and reported a novel compound heterozygous mutation in ARG1 gene (c.263-266delAGAA, p.K88Rfs∗45;c.674T>C,p.L216P) for the first time." (PMID 32769929, 2020). "The patient was diagnosed with argininemia with a novel compound homozygous mutation of the ARG1 gene at the age of 12 years." (PMID 32769929, 2020). "Arginase deficiency (MIM#207800) is a recessive condition caused by mutations in ARG1, a gene mapping on chromosome 6q23.2." (PMID 30853934, 2019). "Mutations in ARG1 (6q23), encoding arginase, the enzyme which catalyzes the hydrolysis of arginine, are the cause of Argininemia (OMIM #207800)." (PMID 26401656, 2015). "Argininemia is caused by autosomal recessive mutations affecting the urea cycle enzyme arginase 1, and this disorder is diagnosed via the measurement of plasma arginine levels." (PMID 25875217, 2015). "Argininemia, a potentially treatable rare urea cycle disorder, was diagnosed in four patients from four different families by exome sequencing, three of them homozygous for ARG1 p.(Thr143Ile) pathogenic variant." (PMID 34782662, 2021). "We reported a Chinese male child presenting with hyperargininemia and progressive spastic diplegia, who has a novel compound heterozygous mutation in the arginase-1 (ARG1) gene (c.263-266delAGAA, p.K88Rfs∗45;c.674T>C,p.L216P), respectively, coming from his mother and father." (PMID 32769929, 2020). "We described a Chinese patient with argininemia who carried a novel mutation in ARG1 gene." (PMID 32769929, 2020). "Indeed, the guanidino compounds alpha-keto-delta-guanidinovaleric acid, alpha-N-acetylarginine, and argininic acid were increased in brain tissue from the Arg1-deficient mouse model of hyperargininemia." (PMID 30853934, 2019). "The identification of ALDH18A1 as new HSP-disease gene (SPG9) pointed toward the identification of a common biochemical pathway where two other well-known IEM-disease-genes (SLC25A15 in HHH syndrome and ARG1 in Argininemia) cause syndromes where spastic paraplegia is present and highly penetrant." (PMID 30853934, 2019). "However, because all patients with ARG1 deficiency in Japan are diagnosed with hyperargininemia based on the blood amino acid analysis, it is very important to perform this test if patients present symptoms such as growth impairment, seizure, paralysis, liver disorder, and cholestasis." (PMID 34646736, 2021). "If arginine analysis had been performed using NBS with MS/MS, hyperargininemia may have been detected prior to the onset of neurological manifestations and the long-term outcome in patients with ARG1 deficiency may have been improved through early intervention." (PMID 34646736, 2021).
arginase deficiency (continued). "Dysfunction or absence of Arg1 activity leads to elevated blood concentrations of arginine, which is called hyperargininemia or argininemia; additionally, di-aminoaciduria (elevated arginine, ornithine, and lysine in the urine) is a biochemical characteristic of the disease." (PMID 40678074, 2025).
type 2 diabetes (16 papers, 2018 to 2026). "In this preliminary study, we demonstrated that rs2781666 SNP in the ARG1 locus is significantly associated with type 2 diabetes." (PMID 34830689, 2021). "It was restricted to one SNP in the ARG1 locus, the polymorphism that has been reported to be associated with type 2 diabetes." (PMID 34830689, 2021). "Our study aimed to investigate the association between ARG1 rs2781666 single nucleotide polymorphism (SNP) and diabetic retinopathy (DR) in type 2 diabetes (T2DM) patients." (PMID 34830689, 2021). "Moreover, the osteoprotegerin SNP rs3134069 is correlated to the higher incidence of DR, and the arginase 1 SNP rs2781666 has a significantly higher susceptibility of DR in the type-2 diabetes population." (PMID 36361470, 2022). "We also identified seven genes (Sardh, Slc39a7, Pfn1, Arg1, Cth, Sod1 and P4hb) in the liver and one gene (Fabp4) in the adipose tissue that may be associated with type 2 diabetes in gerbils." (PMID 29394254, 2018). "The expression of Arg1 has been found to be upregulated in coronary arterioles in humans with type 2 diabetes mellitus (T2DM) and in homogenates of samples of the right atrial appendage collected during cardiac surgery." (PMID 39952693, 2025). "A recent study showed that high levels of arginase 1 and SNPs (rs2781666 and rs2781665) within the ARG1 are associated with increased type 2 diabetes risk." (PMID 36230967, 2022). "Under a pathological condition, an intimate crosstalk between dysfunctional endothelial cells and the circulating RBCs was recently reported where RBCs originated from patients with type 2 diabetes-induced vascular endothelial dysfunction in healthy rat aorta via upregulated vascular ARG1." (PMID 31871538, 2019). "However, our previous works found that inhibition of arginase activity by ABH and knockout arginase 1 in endothelial cells effectively alleviated the enhancement of ROS and vascular inflammation in type 2 diabetes mice model, but TNF-α was not involved." (PMID 30319431, 2018).